PBK (PDZ binding kinase)
Diseases named in the same sentence as PBK in open-access papers (continued):
Sharing a sentence is not in itself a finding about the gene and the disease.
fibrosarcoma (1 paper, 2015). A malignant mesenchymal fibroblastic neoplasm affecting the soft tissue and bone. "It is also interesting to note that PBK/TOPK inhibitor was likewise able to inhibit gelatinase activity in a fibrosarcoma cell line, HT1080, which expresses very high levels of MMP-2 and -9." (PMID 25909225, 2015).
ischemia (1 paper, 2021). A hypoperfusion of the BLOOD through an organ or tissue caused by a PATHOLOGIC CONSTRICTION or obstruction of its BLOOD VESSELS, or an absence of BLOOD CIRCULATION. "Furthermore, ours and other research teams also demonstrated that PBK/TOPK plays crucial roles in ischemic injury and is involved in protection against ischemia and ischemic postconditioning." (PMID 33670114, 2021). "This protective effect of PBK/TOPK in the context of ischemia challenged the development of PBK/TOPK inhibitors in antitumor therapy, and more research is required to further explore its role and underlying mechanisms, to translate its applicability to clinical studies." (PMID 33670114, 2021).
lung squamous cell carcinoma (1 paper, 2022). "In two types of NSCLC, LUAD and lung squamous cell carcinoma (LUSC), the analysis exhibited a positive correlation of PBK/TOPK expression and a certain degree of immune cell infiltration." (PMID 35203508, 2022).
malaria (1 paper, 2014). Malaria is a serious and sometimes fatal disease caused by a parasite that commonly infects a certain type of mosquito which feeds on humans. "In contrast, EryMP numbers are lower in patients with P. vivax and P. malariae malaria, similar to what is observed with the PbK infected mice in our study." (PMID 24651155, 2014).
meningioma (1 paper, 2023). A generally slow growing tumor attached to the dura mater. "Furthermore, of the four DREAM complex target genes shown to be upregulated in type C tumors, only PBK was higher in our NF2-2 meningiomas, while the expression of the 3 other genes (TTK, MELK, and CDK1) was not significantly different between the subgroups." (PMID 36937440, 2023).
nasopharyngeal tumors (1 paper, 2022).
Nephroblastoma (1 paper, 2023). An embryonal neoplasm characterized by the presence of epithelial, mesenchymal, and blastema components. "At the same time, we observed downregulation of some pro-inflammatory factors: TNFRSF21, apolipoprotein E (APOE), nephroblastoma-overexpressed protein (NOV), and PDZ-binding protein (PBK)." (PMID 36829800, 2023).
Solid Pseudopapillary Neoplasm of the Pancreas (1 paper, 2016). A low-grade malignant neoplasm that arises from the exocrine pancreas. "Eighteen cases of solid pseudopapillary neoplasms of the pancreas were evaluated for RNA expression levels of FLI1, DKK1, INPP5D (SHIP1), IGFBP3, PBK (TOPK), and BCL9 and BCL9L." (PMID 27539223, 2016).
thymoma (1 paper, 2021). A neoplasm arising from the epithelial cells of the thymus. "PBK expression in KIRC, liver hepatocellular carcinoma, THCA, and thymoma was positively correlated with the infiltration of immune cells including B cells, CD4+T cells, CD8+ T cells, macrophages, monocytes, and neutrophils." (PMID 34859058, 2021).
vitiligo (1 paper, 2021). Generalized well circumscribed patches of leukoderma that are generally distributed over symmetric body locations and is due to autoimmune destruction of melanocytes. "With the framework, we had successfully predicted and experimentally validated that some potential therapeutic targets such as CDK1 and PBK were closely related to melanogenesis, and further explored the multi-target strategy of kaempferide for vitiligo through proteomics profiling." (PMID 34603063, 2021). "These articulation proteins mainly included TXN (Thioredoxin), PBK, CDK1 (Cyclin-dependent kinase 1), which may be served as potential therapeutic targets for vitiligo." (PMID 34603063, 2021).
ZIKV infection (1 paper, 2018). "Genes associated with cell differentiation and proliferation, such as BUB1, DLGAP5, PBK and CEP55 (Cluster 3) were upregulated during DENV infection but not ZIKV, while EGR1, HBEGF and MAFB (Cluster 4), were up-regulated at d17 POS during ZIKV infection." (PMID 30596671, 2018).
tumor (131 papers, 2008 to 2026). "Studies have shown that high expression of the PBK protein in tumor cells is associated with tumor progression and prognosis." (PMID 39628686, 2024). "The results above showed that PBK expression is positively associated with the stage of the cancer in most tumor types." (PMID 34859049, 2021). "We also analyzed the relationships between PBK expression, mutation and methylation status, clinical outcome, and tumor immune infiltration in cancers, and screened drugs that can potentially inhibit PBK." (PMID 34859058, 2021). "The mitotic kinase T‐LAK cell‐originated protein kinase/PDZ‐binding kinase (TOPK/PBK) is associated with proliferation of tumor cells, maintenance of cancer stem cells, and poor patient prognosis in many cancers." (PMID 31714026, 2020). "Here we show that PBK expression is increased and associated with larger tumor size, presence of vascular invasion, lymph node metastasis and poor overall and disease-free survivals in two independent cohorts of 879 patients with HCC." (PMID 28525379, 2017). "High PBK expression was significantly associated with larger tumor size (P = 0.001), vascular invasion (P = 0.003) and tumor lymph node metastasis (P = 0.019)." (PMID 28525379, 2017). "Similarly to OIP5, PBK expression correlates with features of genomic instability such as high tumor mutational burden and microsatellite instability." (PMID 38596293, 2024). "Additionally, high PBK/TOPK expression was associated with mutations in DNA damage repair genes, and thus with increased tumor mutation and neoantigen burden." (PMID 35203508, 2022). "We activate Raf/MEK/ERK and PBK/Akt/mTOR pathways through autophosphorylation of receptor tyrosine kinases, causing uncontrolled cell division, proliferation, and transformation, stimulating neovascularization, and promoting tumor growth and metastasis." (PMID 35035522, 2022). "Finally, we found that PBK is associated with sensitivity and resistance to various anticancer drugs and is related to drug-targeted genes in tumor cells." (PMID 34859058, 2021). "Elevated PBK expression may be linked to greater tumor malignancy and worse prognosis." (PMID 39649886, 2024). "The tumor diagnostic model was formulated as follows: logit (P-HCC) = -2.534 – 1.240 * SOCS2 expression level - 1.320 * LCAT expression level + 0.335 * FTCD expression level – 1.911 * KRT17 expression level + 4.422 * PBK expression level + 2.006 * CBX2 expression level." (PMID 36159831, 2022). "Furthermore, several recent studies have suggested that PBK/TOPK may be associated with tumor-infiltrating immune cells and have a potential target for cancer immunotherapy." (PMID 34603451, 2021). "In vivo, PBK gene expression primarily occurs in proliferative tissues and organs, such as embryonic and tumor tissues." (PMID 39628686, 2024). "In summary, PBK promotes tumor proliferation and metastasis and is closely related to tumor grading and patient prognosis." (PMID 39649886, 2024). "In conclusion, this study was designed to explore the DEGs potentially regulated by PBK, analyze the effects of these DEGs on tumor formation and progression, and evaluate their value as biomarkers." (PMID 39649886, 2024). "Aberrant PBK expression occurs in various tumors and is closely related to tumor cell proliferation, metastasis, tumor grading, and patient prognosis." (PMID 39649886, 2024). "Findings regarding the function of PBK in the aggressive tumor cells were validated by siRNA knockdown, overexpression, and transwell experiments." (PMID 38167466, 2024). "In LUAD patients with high PBK expression, immune score, stromal score and tumor purity were substantially decreased." (PMID 37993518, 2023). "Second, we also observed that PBK low expression was highly enriched in tumor metabolism-related pathways, including the HEDGEHOG pathway, and XENOBIOTIC, fatty acids, and BILE ACID METABOLISM." (PMID 37993518, 2023).
tumor (continued). "Consistently, we validated PBK expression in the GSE116959, GSE19188 and CPTAC-LUAD cohort with increased PBK mRNA and protein levels in tumor samples." (PMID 37993518, 2023). "These putative positive correlations show that a high CDK1/PBK/CHEK1 expression promotes tumor growth, aggressiveness, and immune evasion through the increased recruitment of T Cells CD4+ Th2, MDSCs, and TAM-M2, all of which have pro-tumor effects." (PMID 38003585, 2023). "PBK is a MAPKK-like protein kinase, and its high expression is associated with multiple aggressive cancer phenotypes, and PBK is considered a potential molecular target for tumor diagnosis and targeted therapy." (PMID 36984548, 2023). "Low expression of PBK had a better anti-tumor immune activation phenomenon, which was demonstrated by the highest expression levels of most immunosuppressants and some immunostimulants." (PMID 37993518, 2023). "Many studies about the possible role of PBK in tumor immune cell infiltration have emerged in recent years." (PMID 35065633, 2022). "Except for the subgroup of gender, the expression of PBK is higher in Asian patients under 60 with tumor stageIII+IV." (PMID 35065633, 2022). "The association between PBK mRNA expression and the clinicopathological characteristics of HCC patients including gender, race, tumor stage, and age was investigated using TCGA data." (PMID 35065633, 2022). "It’s the first time to reveal that the expression of PBK is closely related to age, race, and tumor stage." (PMID 35065633, 2022). "The up-regulated apoptotic protein level and NFκB activity evoked by PBK overexpression were also counteracted by using JSH-23 in tumor tissues." (PMID 35859118, 2022). "PBK expression was significantly correlated with race (P=0.0024), tumor stage (P=0.0089), and age (P=0.0131), except for gender (P=0.2998) in HCC patients." (PMID 35065633, 2022). "Thus, PBK is associated with survival outcome in a variety of cancers and may promote tumor development and progression by increasing immune cell infiltration into the tumor microenvironment." (PMID 34859058, 2021). "PBK is overexpressed in a variety of active proliferating cells including malignant tumor cells as well as normal sperm cells." (PMID 34859058, 2021). "Meanwhile, we also found that PBK expression was correlated with the tumor stage in various cancers." (PMID 34859049, 2021). "We next investigated the PBK expression in different tumor stages across cancers and compared the expression in different stages in each tumor type." (PMID 34859049, 2021). "We first compared the methylation status of tumor and normal tissues in 14 cancer types and found that PBK methylation was decreased in THCA, LIHC, and LUAD." (PMID 34859058, 2021). "We next compared the difference of PBK mRNA expression between cancer and normal tissues on TCGA database, and the results showed that PBK was relatively highly expressed in most tumor tissues (p < 0.05), except for SKCM, THYM, and READ." (PMID 34859049, 2021). "The results of the functional enrichment analysis suggested that PBK and related genes contribute to tumor development via cell cycle regulation." (PMID 34859058, 2021). "Due to the broad expression of PBK across multiple tumor types, specific inhibitors have been developed to target PBK, including HI-TOPK-03241, OTS514/OTS96442, and ADA-0743, and show high therapeutic potency in the preclinical study." (PMID 33431797, 2021). "Integration of our transcriptomic and immunopeptidomic analyses revealed high-affinity peptides derived from tumor-associated genes such as PRAME, PBK, and several MAGE gene family genes." (PMID 34818552, 2021).
tumor (continued). "Further analysis showed that PBK is negatively correlated with the immune and stromal scores in most cancer types, which indicated that the PBK expression level is negatively correlated with tumor immune infiltration." (PMID 34859049, 2021). "Our results showed that PBK expression in various types of tumor was related to TMB and MSI, although additional studies are needed in order to determine the significance of this observation in terms of response to immunotherapy." (PMID 34859058, 2021). "Functional enrichment analysis showed that PBK and its related genes regulate tumor-related signaling pathways." (PMID 34859058, 2021). "As a mitotic kinase, PBK plays an important role in the process of tumorigenesis and tumor progression." (PMID 34603451, 2021). "The results of this study showed the potential correlation and mechanism of PBK/TOPK and tumor-immune interactions." (PMID 34603451, 2021). "Next, the expression of PBK in 21 tumor cell lines based on the CCLE database showed that PBK displayed inconsistent expression levels across tumor cell lines (p = 2.2e-16), and the expression of the PBK level was relatively high in tumor cells." (PMID 34859049, 2021). "PBK is upregulated in higher tumor stages in most cancers including BRCA, ESCA, KICH, KIRC, KIRP, and LUAD." (PMID 34859049, 2021). "PDZ binding kinase (PBK)/T-LAK cell-derived protein kinase (TOPK) is an important mitotic kinase that promotes tumor progression in some cancers." (PMID 34603451, 2021). "Different public databases were used to analyze the PBK expression in tumor and normal samples and the relationship with different cancers." (PMID 34859049, 2021). "Herein, our findings provide new insight into understanding the potential role of PBK in tumor immunology." (PMID 33431797, 2021). "The results showed that PBK knockdown significantly increased the percentage of lysis TW03 cells when the tumor cells were cocultured with CD3/CD28-activated human HLA-A2+ T lymphocytes, and this increase was markedly reversed by the recovery of CD276." (PMID 33431797, 2021). "This was confirmed by RNAscope analysis performed on three out of six genes (BIRC5, CDK1, and PBK), showing their predominant expression on tumor cells of NB patients." (PMID 33239635, 2020). "MST screening was performed as a novel way to screen a selective PBK/TOPK inhibitor from several potential anti-tumor natural compounds." (PMID 30898980, 2019). "In metastatic PrCa, tissue PBK transcript was upregulated in all three clinical cohorts when compared with benign and primary tumours (p = 0.0002, Grasso; p = 4.3e-14, Taylor; p = 6.3e-10, Varambally)." (PMID 30237440, 2019). "PBK is primarily nuclear in tumours, where its expression is restricted to epithelia and is significantly enhanced in CRPC compared with matched benign prostate tissue." (PMID 30237440, 2019). "These experiments provide robust experimental evidence for the key role of PBK in sustaining AR levels and tumour growth, indicating that PBK is an essential player in PrCa cell survival and invasion." (PMID 30237440, 2019). "Transcriptome sequencing revealed that PBK is a mediator of global AR signalling with key roles in regulating tumour invasion and metastasis." (PMID 30237440, 2019). "Taken together, our results showed that baicalin inhibited tumor growth by suppressing PBK/TOPK activities in vivo." (PMID 30898980, 2019). "For example, PBK/TOPK is upregulated during the cytogenesis of tumor cells, most likely by phosphorylation of Thr9 and activation by cyclin B1/cdk1." (PMID 30286126, 2018).
tumor (continued). "Correlation between miR-770-5p and PBK mRNA levels in tumor tissues was normalized and assessed using the Pearson correlation coefficient, and the R-value indicated a negative correlation between miR-770-5p and PBK expression (R=−0.656)." (PMID 28333152, 2017). "Patients with high PBK mRNA expression survived much shorter and experienced short period of tumor relapse or metastasis." (PMID 28525379, 2017). "To confirm that reduction of PBK expression was due to the effects of miR-770-5p transfection in vivo, we analyzed miR-770-5p and PBK mRNA levels using quantitative reverse transcription-PCR (qRT-PCR) in tumor tissues." (PMID 28333152, 2017). "Paired tissue analysis in 3 evaluable patients also identified PLK1, BUB1, and PBK as the top genes overexpressed in tumor relative to adjacent normal samples." (PMID 28423512, 2017). "Western blot analysis demonstrated that PBK expression was attenuated in tumor tissues bearing miR-770-5p." (PMID 28333152, 2017). "Our data demonstrated that PBK promoted tumor growth and metastasis via activating β-Catenin signaling pathway which plenty of chemotherapeutic agents target." (PMID 28525379, 2017). "The results support the suggestion that PBK/TOPK can serve as a valuable target for the development of tumor diagnosis and immunotherapy, although our findings need to be confirmed by further studies." (PMID 27347940, 2016). "We were also intrigued to see some positive immunostaining for PBK/TOPK in the basal layer of epithelial cells in non-tumor tissue sections adjacent to cancer tissue, suggesting a possible role for PBK/TOPK in this cell type." (PMID 25909225, 2015). "For the transcriptome analysis of PBK inhibitor–treated samples; T65, T08 and T59 tumor cultures were treated with PBK inhibitor at a concentration of 5 μm (all in triplicate)." (PMID 26081429, 2015). "Taken together, these results suggest that targeting PBK/TOPK by pharmacological agent is sufficient to ameliorate multiple facets of the tumor phenotype, and therefore, PBK/TOPK is a potentially important therapeutic target." (PMID 25909225, 2015). "Other examples include MCM10 and CCND1 also targeted by miR-199a-5p, PBK, that promotes tumour cell proliferation through p38 MAPK activity that is targeted by miR-28-5p and cyclin genes CCND1 and CCND2 targeted by miR-150." (PMID 25200074, 2014). "UHRF1 and PBK had increased expression in all tumour samples relatively to normal tissue samples, but the highest expression levels were detected in PDTC." (PMID 19809427, 2009). "Based on this, we hypothesized that PBK may regulate the expression and activity of EIF4E, suggesting that the PBK/EIF4E pathway is likely to be an important tumor-associated pathway." (PMID 39649886, 2024). "In this study, small interfering RNA (siRNA) targeting PBK was chosen as the therapeutic agent, and nanotechnology was utilized to enhance its stability and bioavailability in vivo, thereby achieving specific responsiveness to the tumor microenvironment." (PMID 39628686, 2024). "The over-expression of PBK could promote both tumor cell proliferation and migration, and it was also significantly associated with poor prognosis in PitNET patients." (PMID 38167466, 2024). "In short, the literature suggests that PBK is a gene closely related to tumor development, and altering its expression will inevitably lead to changes in tumor-related biological phenotypes and molecular signaling pathways, consistent with our data and analysis." (PMID 39649886, 2024). "Overexpression of PBK (PDZ Binding Kinase) may lead to increased proliferation and survival ability of tumor cells." (PMID 38244584, 2024). "Here, we investigate the role of the LIN28B pathway in G3 MB and demonstrate that the LIN28B–lethal‐7 (let‐7; a microRNA that is a tumor suppressor)–lymphokine‐activated killer T‐cell‐originated protein kinase (PBK; also known as PDZ‐binding kinase) axis promotes G3 MB proliferation." (PMID 37341142, 2023).